SDC1 (syndecan 1)
Diseases named in the same sentence as SDC1 in open-access papers (continued):
Sharing a sentence is not in itself a finding about the gene and the disease.
nephrotic syndrome (1 paper, 2018). A collection of symptoms that include severe edema, proteinuria, and hypoalbuminemia; it is indicative of renal dysfunction. "To further investigate the role of AGPT-2 in glycocalyx endothelial damage, we evaluated if the association between LDL-cholesterol (the only nephrotic syndrome feature independently associated with syndecan-1) was mediated by AGPT-2." (PMID 30384404, 2018). "We reported the association of syndecan-1 with several features of nephrotic syndrome, such as the lipid profile and 24 h urinary protein excretion rate." (PMID 30384404, 2018). "Mediation analyses were performed to assess the hypothesized associations of nephrotic syndrome features and AGPT2 with syndecan-1." (PMID 30384404, 2018). "Finally, because we did not have follow-up data on these patients, is not possible to evaluate if AGPT-2 and syndecan-1 returned to basal levels after nephrotic syndrome remission." (PMID 30384404, 2018).
odontogenic tumor (1 paper, 2013).
Pancreatic cysts (1 paper, 2024). A cyst of the pancreas that possess a lining of mucous epithelium. "This was also true for median serum level of SDC1 which were elevated in PDAC compared with pancreatic cysts patients (43.3 ng/mL [IQR 32.2–71.2] vs. 30.1 ng/mL [IQR 26.5–35.4], respectively; p < 0.001)." (PMID 39263943, 2024). "We thus aimed to evaluate the diagnostic and prognostic performance of serum MMP‐7 and SDC1 as potential biomarkers, separately and combined, and as adjunct to CA 19‐9, in patients with PDAC and pancreatic cysts." (PMID 39263943, 2024).
papillary carcinoma (1 paper, 2015). A malignant epithelial neoplasm characterized by a papillary growth pattern. "A tissue microarray analysis of SDC1 expression in papillary carcinomas of the thyroid indicated that SDC1 was mainly expressed in the cytoplasm of epithelial cells and stroma of papillary carcinomas of the thyroid." (PMID 26293675, 2015).
parasite (1 paper, 2021). "Our analysis shows that measuring a combination of host parameters (e.g. Syndecan-1, IL-6, platelet levels) and total parasite biomass (PvLDH) could predict the extent of parasite infection outside of circulation." (PMID 34585667, 2021).
Peritoneal Fibrosis (1 paper, 2016). Disorder characterized by a wide range of structural changes in PERITONEUM, resulting from fibrogenic or inflammatory processes. "This study indicates that, while syndecan-1 is important for providing a barrier to acute S. aureus infection in PD, it does not affect peritoneal fibrosis and angiogenesis." (PMID 26832929, 2016).
peritoneal mesothelioma (1 paper, 2019). A benign or malignant mesothelial neoplasm that arises from the peritoneum. "A low frequency of Syndecan-1 expression (10%) has recently also been described for peritoneal mesothelioma." (PMID 31976021, 2019).
pheochromocytoma (1 paper, 2019). "In vitro studies have shown that the human laminin α2 large globular 1 domain exhibits cell adhesion activity and binds to syndecan-1, which was proven in the cultured PC12 cell line from transplantable rat pheochromocytoma." (PMID 31618810, 2019).
placental diseases (1 paper, 2021). "We performed a series of analyses to assess whether syndecan-1 was reduced in these three clinical outcomes (which all represent placental diseases)." (PMID 34400721, 2021).
prion disease (1 paper, 2021). A transmissible disease that is caused by a protein that is able to induce abnormal folding of normal cellular proteins, leading to characteristic spongiform brain changes, which are associated with neuronal loss without an inflammatory response. "IL-34 and Syndecan-1 also increased in APP cKO, especially at 6 months of age, and IL34 was recently proposed to be the main brain factor to stimulate proliferation of microglia in the ME7 model of prion disease." (PMID 33402196, 2021).
Psoriasiform dermatitis (1 paper, 2020). A skin abnormality characterized by redness and irritation, with thick, red skin that displays flaky, silver-white patches (scales). "Another report showed that syndecan-1 regulates pro-inflammatory cytokine IL-17 during Psoriasiform Dermatitis, where the absence of syndecan-1 resulted in increased skin inflammation." (PMID 32133006, 2020).
renal carcinoma (1 paper, 2020). A carcinoma arising from the epithelium of the renal parenchyma or the renal pelvis. "The degree of syndecan-1 loss in carcinomas often correlates with histological grade and indicates poor prognosis, as shown in head and neck, hepatocellular, colorectal, cervical, pancreatic, renal carcinomas, and bladder cancers." (PMID 32977498, 2020).
Respiratory distress (1 paper, 2015). Respiratory distress is objectively observable as the physical or emotional consequences from the experience of dyspnea. "The rs11899121 (SDC1) SNP was associated with a approximately 49% reduction in risk of respiratory distress (OR for CG/GG vs CC genotypes, 0.505; P = .0025)." (PMID 25805752, 2015).
salivary gland neoplasm (1 paper, 2021). Tumors of the SALIVARY GLANDS. "We aimed to assess the immunopositivity of syndecan-1 in epithelial and stromal components of salivary gland neoplasms and to compare it between benign and malignant subtypes in addition to evaluating its correlation with clinicopathologic parameters." (PMID 31540870, 2021).
salivary gland tumors (1 paper, 2021). "According to our findings we postulate that stromal syndecan-1 correlates with the behavior of salivary gland tumors, with malignant neoplasms demonstrating a higher expression, indicating a role for syndecan-1 in invasion and metastasis." (PMID 31540870, 2021). "We showed a significant difference in the expression of syndecan-1 between both neoplastic cells and stroma of the studied salivary gland tumors." (PMID 31540870, 2021). "Syndecan-1 seems to play a role in the pathogenesis of salivary gland tumors." (PMID 31540870, 2021). "All tumors examined in this study showed the expression of syndecan-1 in tumor cells, suggesting that CD138 may contribute to the pathogenesis of salivary gland tumors." (PMID 31540870, 2021). "Despite many reports on the roles of syndecan-1 in the tumorigenesis of different kinds of neoplasms, the expression and functional details of this protein in salivary gland tumors is not clear." (PMID 31540870, 2021).
seminoma (1 paper, 2023). A radiosensitive malignant germ cell tumor found in the testis (especially undescended), and extragonadal sites (anterior mediastinum and pineal gland). "To further examine the functions of MMP9 and CTSK in seminoma, we subset immune cells (PTPRC+), and explored the expression patterns of markers for T cells (CD3D+ and CD3E+) and B cells (CD79B+; MS4A1+ and SDC1+)." (PMID 38123589, 2023).
Sjögren's syndrome (1 paper, 2023). "SDC1 level is associated with salivary gland function and inflammation in patients with Sjögren's syndrome and it is increased in saliva." (PMID 38129923, 2023).
squamous cell carcinoma of the esophagus (1 paper, 2025). "Alterations of Syndecan-1 expression in the tumor stroma have also been suggested for squamous cell carcinoma of the esophagus." (PMID 40943808, 2025).
staphylococcal infection (1 paper, 2023). An infection caused by Staphylococcus. "Here, we define the role of CD9 in staphylococcal adherence and uptake, observing that CD9 coordinates syndecan-1, fibronectin, and β1 integrins to allow efficient staphylococcal infection." (PMID 37486132, 2023). "However, some studies have suggested that while SDC-1 is important for staphylococcal infection, it is not a direct receptor." (PMID 37486132, 2023).
steatosis (1 paper, 2019). Increased lipid within the cytoplasm of cells. "Neither syndecan-1, heparan sulfate nor chondroitin sulfate levels correlated with graft steatosis, cold ischemic time, postoperative liver function or MEAF-score." (PMID 31415628, 2019).
Stillbirth (1 paper, 2021). Death of the fetus in utero after at least 22 weeks of gestation. "It confirms syndecan-1 as a potential biomarker that could be integrated into a multi-marker test to improve the detection of compromised fetal growth to reduce the burden of preventable stillbirth." (PMID 34400721, 2021).
Ta (1 paper, 2005). "Among the mostly changed genes between normal bladder and Ta tumours, we found genes related to the cytoskeleton (keratin 7 and syndecan 1), and transcription (high mobility group AT-hook 1)." (PMID 16265353, 2005). "SDC1 is usually located to the cell membrane, and our finding of a cytoplasmic staning pattern in Ta tumours suggests a failure in intracellular trafficking, and could indicate loss of a functional SDC1 protein." (PMID 16265353, 2005).
thalassemia (1 paper, 2015). An inherited blood disorder characterized by a decreased synthesis of one of the polypeptide chains that form hemoglobin. "The new candidates accounted for the remaining 19.2% of the explainable variation, with USP38 (8.1%), DDC (3.8%), FREM3 (3.0%), SDC1 (2.6%), and LOC727982 (1.7%) all accounting for more variation than ABO blood group and α-thalassemia but in aggregate less than the sickle HbAS polymorphism." (PMID 25805752, 2015).
thrombotic thrombocytopenic purpura (1 paper, 2024). "Although these clinical cohort studies identified syndecan-1 as a biomarker or predictor of patient outcomes, the function of syndecan-1 in thrombotic thrombocytopenic purpura remains undefined." (PMID 38912739, 2024).
tongue cancer (1 paper, 2023). A malignant neoplasm affecting the tongue. "The reliance of HNSCC on IGF1R coupled to Sdc1 was initially examined by screening the UM-SCC47 and SCC25 tongue carcinoma cell lines for their response to active or inactive mSSTNIGF1R peptides." (PMID 36968227, 2023).
Tricuspid regurgitation (1 paper, 2020). Failure of the tricuspid valve to close sufficiently upon contraction of the right ventricle, causing blood to regurgitate (flow backward) into the right atrium. "In the high syndecan-1 group, severe tricuspid regurgitation (42.4% vs. 17.8%, p < 0.001) was more frequent when compared with the low syndecan-1 group." (PMID 32531891, 2020). "Our results also showed that severe tricuspid regurgitation was more frequent in patients with high preoperative syndecan-1." (PMID 32531891, 2020). "Severe tricuspid regurgitation was more frequent, and baseline right ventricular systolic pressure was significantly greater in patients with high preoperative syndecan-1." (PMID 32531891, 2020).
vivax malaria (1 paper, 2021). "In patients with vivax malaria there was a trend towards higher median plasma syndecan-1 in males compared to females (158 [IQR 118–229] vs. 109 ng/ml, p = 0.068), and lower S-1-P (1.82 [IQR 1.24–2.64] vs. 3.2 [IQR 1.44–3.85] μM, p = 0.07)." (PMID 33963210, 2021). "Syndecan-1 was also associated with the adhesion molecule ICAM-1 in both knowlesi and vivax malaria." (PMID 33963210, 2021). "In vivax malaria, neither urinary GAGs nor plasma syndecan-1 were independently associated with risk for severe disease, or AKI." (PMID 33963210, 2021). "Syndecan-1 also correlated with endothelial activation (ICAM-1, angiopoietin-2) and ADMA in vivax malaria." (PMID 33963210, 2021). "In this study, we measured concentrations of the glycocalyx breakdown products plasma syndecan-1 and urinary GAGs, and plasma concentrations of ADMA, in Malaysian adults with severe and non-severe knowlesi and vivax malaria, and in healthy controls." (PMID 33963210, 2021).
tumor (714 papers, 1994 to 2026). "SDC1 (Syndecan-1) plays a role in cell-matrix interactions and has been implicated in tumor progression and metastasis." (PMID 40226632, 2025). "Higher levels of syndecan-1 are associated with greater tumour size, enhanced malignancy, promotion of angiogenesis, and greater risk of metastasis." (PMID 41463344, 2025). "SDC1 is a heparin cell surface proteoglycan that acts as a co-receptor for growth factors and chemokines, and it is significantly associated with tumor aggressiveness and clinical outcomes." (PMID 41364407, 2025). "Subgroup analysis of clinical factors further revealed that the association between SDC1 expression in tumor cells and OS was particularly evident in patients aged 50 years or older, post-menopausal women, tumors ≤ 2 cm, and those with 0–3 nodal involvement." (PMID 41364407, 2025). "In subtype analysis, SDC1 expression in tumor cells was associated with OS in the luminal subtype (HR: 1.82 (1.02, 3.25), P = 0.04), but not in human epidermal growth factor receptor 2 (HER2)-positive or triple-negative subtypes." (PMID 41364407, 2025). "In the analysis of clinical subtypes, findings revealed that in older patients, particularly those aged 50 and above and post-menopausal, the expression of SDC1 in tumor cells was significantly linked to overall survival (OS), unlike in younger patients." (PMID 41364407, 2025). "SDC1 is inherently expressed at high levels on MM cell surfaces and is known to be shed into the tumor microenvironment, a feature linked to MM pathogenesis." (PMID 39175546, 2024). "Loss of syndecan-1 expression in tumor cells leads to reduced cell–cell cohesion, increasing the potential for tumor invasion and metastasis." (PMID 39728992, 2024). "The loss of syndecan-1 from the cell membrane decreases epithelial cell adhesion, reducing binding to the extracellular matrix and facilitating tumor cell migration and invasion." (PMID 39728992, 2024). "SDC1 exhibited a greater tumor mutational burden (TMB) score, while ERBB2, KDR, FGF2, KIT, FGFR1, and FGF1 showed lower TMB scores." (PMID 38189813, 2024). "We also observed a statistically significant relationship with the number of mitoses, suggesting that increased proliferation of tumor cells is associated with decreased syndecan-1 expression." (PMID 39728992, 2024). "The SDC1 expression in tumor and cancer associated fibroblasts (CAFs) was then observed in 282 TNBC patients by immunohistochemistry." (PMID 37069585, 2023). "The accumulation and differentiation of SDC1/CD138+ IgG-producing PCs can be modulated by tumor-associated neutrophils and myeloid-derived suppressor cells in a BAFF- or STAT3-dependent manner." (PMID 37138324, 2023). "In our research, the associations between SDC1 in tumor cells and CAFs with TILs and related cytokines need to be further confirmed in in vivo and in vitro studies." (PMID 37069585, 2023). "A report showed that low SDC1 expression was associated with metastatic potential, tumor recurrence, and shortened overall survival in CRC patients." (PMID 38132443, 2023). "The patients with positive expression of SDC1 in tumor cells were associated with lower TIL distribution (p = 0.021)." (PMID 37069585, 2023). "In contrast, increased syndecan-1 expression in breast, pancreatic, ovarian, thyroid, and endometrial tumors is associated with tumor progression and poor prognosis." (PMID 36693448, 2023). "SDC1 encodes essential cell surface adhesion molecules that maintain cell morphology and a stable microenvironment and promotes tumor progression by stimulating cell proliferation, metastasis, invasion, and angiogenesis." (PMID 36131343, 2022). "Prior observations have indicated that chemotherapy can cause shedding of the syndecan-1 proteoglycan to accelerate tumor recurrence and progression." (PMID 34490087, 2021).
tumor (continued). "There was an association between low syndecan-1 expression and nodal (p=0.003) and distant (p=0.001) metastasis, lymphovascular invasion (p=0.001), and tumor recurrence (p=0.006)." (PMID 33437261, 2021). "Low syndecan-1 expression was associated with nodal involvement, distant metastasis, lymphovascular invasion, and tumor recurrence." (PMID 33437261, 2021). "The lack of Fasn upregulation in hSDC1+/+ DEN indicated the potential of overexpressed SDC1 to modulate tumor-associated changes in intermediary metabolism." (PMID 33801718, 2021). "In MM, the expression of SDC-1 is generally low but when present, SDC-1 associates to epithelioid differentiation, inhibition of tumor cell migration and favorable prognosis, meanwhile SDC-1 decrease deteriorates the prognosis." (PMID 33562126, 2021). "Loss of syndecan-1 immunoexpression is associated with metastatic potential, tumor recurrence and shorter survival in CRC and is considered a potential biomarker of poor prognosis in CRC patients." (PMID 33437261, 2021). "Low expression of syndecan-1 showed an association with nodal (p=0.003) and distant (p=0.001) metastasis, lymphovascular invasion (p=0.001), and tumor recurrence (p=0.006)." (PMID 33437261, 2021). "Immunohistochemistry of tumorous specimens revealed that while cell surface syndecan-1 expression was reduced on cancer cells, it appeared on the surface of tumor-associated fibroblasts." (PMID 32388727, 2020). "In BC, we previously demonstrated that high preoperative serum levels of SDC1 are associated with progressed tumor stages, the presence of lymph node metastases, and are independently associated with poor patient survival." (PMID 33114033, 2020). "This raises a possibility that high tumor stiffness promotes a mesenchymal-like phenotype in cancer cells, which in turn leads to the loss of Sdc-1, among other consequences." (PMID 33330449, 2020). "SDC-1 is associated with proliferation through its interaction with growth factors and is often upregulated in cancer cells during tumour progression." (PMID 32485953, 2020). "The interactions between LAMA3 subunit of laminin 332 with α6β4 integrin and syndecan 1 leads to the activation of protein kinase C (PKC) pathway which causes tumor cell migration and invasion." (PMID 31409848, 2019). "Immunoexpression of SDC1 was noted to be inversely association with tumor stage (80.9% Ta vs. 58.6% T2 vs. 40% >T2, p < 0.0001)." (PMID 31905599, 2019). "In agreement with other analyses of CRC, the loss of epithelial SDC1 was correlated with tumor TNM stage, and the incidence of metastasis was correlated with local lymph nodes." (PMID 31182980, 2019). "Our data also correlate well with other previous immunohistochemical studies which have described a loss of expression of syndecan-1 in CRCs, some of which have been found to correlate with tumor stage and metastasis." (PMID 29940912, 2018). "Syndecan-1 (SDC1) is a heparin sulfate proteoglycan, which has been linked with the prognosis and treatment response in a various tumor type." (PMID 29340066, 2017). "Studies indicate that SDC1 expression varies among cancer types and that differential expression in stromal compartments and carcinoma cells are strongly associated with tumor aggressiveness and clinical outcomes." (PMID 28422726, 2017). "SDC1 is a heparin cell surface proteoglycan acting as a co-receptor for growth factors and chemokines, which strongly associated with the tumor aggressiveness and clinical outcomes." (PMID 29340066, 2017). "Although syndecan-1 has been detected in the nuclear compartment of various tumor types, the functions associated with nuclear translocation remain incompletely understood." (PMID 29216821, 2017). "Cytoplasmic overexpression of syndecan-1 in cancer cells, often accentuated close to the nucleus, was demonstrated in Ta tumours compared to normal urothelium, suggesting a failure in intracellular trafficking caused by the loss of functional syndecan-1." (PMID 29207682, 2017).